CTAGE9 (CTAGE family member 9)
Tractability: Antibody: UniProt predicts a signal peptide or a membrane-spanning region.
Gene: Protein-coding gene on chromosome 6 (131,708,441 to 131,711,017, reverse strand). Ensembl gene ENSG00000236761.
Subcellular location: Membrane
Gene Ontology:
Biological process: endoplasmic reticulum to Golgi vesicle-mediated transport; protein secretion; vesicle cargo loading
Cellular component: endoplasmic reticulum exit site; endoplasmic reticulum membrane; membrane
Genetic constraint (gnomAD): Loss-of-function variants: 0 observed, 1.03 expected, observed/expected ratio (o/e) 0, 90% interval 0 to 1.71. That is too few expected variants to judge how well the gene tolerates losing a copy. Missense variants: 248 observed, 668.77 expected, observed/expected ratio (o/e) 0.37, 90% interval 0.33 to 0.41. Synonymous variants: 105 observed, 233.5 expected, observed/expected ratio (o/e) 0.45, 90% interval 0.38 to 0.53.
Homologues: Orthologues: dog MIA2 (76% identical), mouse Mia2 (68% identical), rat Mia2 (68% identical), Drosophila melanogaster Tango1 (21% identical). Paralogues in human: CTAGE4 (99% identical), CTAGE8 (99% identical), CTAGE15 (96% identical), CTAGE6 (95% identical), MIA2 (83% identical), CTAGE1 (75% identical), MIA3 (27% identical), SPZ1 (8% identical), MIA (2% identical), OTOR (1% identical).
Diseases named in the same sentence as CTAGE9 in open-access papers:
CTAGE9 is named in the same sentence as 1 disease in open-access papers, as found by Europe PMC text mining. Sharing a sentence is not in itself a finding about the gene and the disease. The quoted sentences say what the papers report.
cancer (1 paper, 2024). A tumor composed of atypical neoplastic, often pleomorphic cells that invade other tissues. "Many of these genes are specifically expressed in reproductive organs and germ cells and aberrantly expressed in several human cancers, but there are limited data in the literature regarding the expression of CTAGE9." (PMID 38791358, 2024). "The other gene specifically highly expressed during the MS phase, CTAGE9, belongs to the CTAGE family (cancer/testis antigen family), which exhibits rapid and primate-specific expansion." (PMID 38791358, 2024).